GOLPH3 (golgi phosphoprotein 3)
Diseases named in the same sentence as GOLPH3 in open-access papers (continued):
Sharing a sentence is not in itself a finding about the gene and the disease.
gastric cancer (continued). "Interestingly, the rates of high GOLPH3 expression were 75.00% (60 out of 80) in gastric cancer tissues, 43.75% (35 out of 80) in carcinoma-adjacent tissues and 12.50% (10 out of 80) in normal tissues, respectively." (PMID 25286393, 2014). "Based on these results, we speculate that GOLPH3 might be affected progression and metastasis of gastric cancer through the activation of Akt/mTOR signaling pathway." (PMID 25286393, 2014). "In particular, significantly higher GOLPH3 expression was accompanied by high expression of p-mTOR, p-4E-BP1, and p-p70S6 in gastric cancer tissues, and this relationship was significantly associated with the depth of invasion, histological grade, and lymph node and distant metastasis." (PMID 25286393, 2014). "GOLPH3 combined with Akt/mTOR signaling activation may play an important role in the development, differentiation, invasion and metastasis of gastric cancer." (PMID 25286393, 2014). "Finally, the invasion and migration mechanisms of GOLPH3 in gastric cancer still need further investigation." (PMID 25286393, 2014). "However, the precise mechanisms underlying this relationship are unclear, and the exact molecular mechanism by which GOLPH3 is involved in gastric cancer tumorigenesis, invasion and metastasis is poorly understood." (PMID 25286393, 2014). "Moreover, we propose that the inhibition of the expression of genes in the GOLPH3 and mTOR signaling pathway may represent a novel target for gastric cancer therapy." (PMID 25286393, 2014). "In this study, we investigated clinical significances of GOLPH3 and AKT/mTOR signaling in gastric cancer." (PMID 25286393, 2014). "The mRNA expression levels of GOLPH3, mTOR, Akt, p70S6 and 4E-BP1 in gastric cancer, carcinoma-adjacent and paired normal tissue were analyzed using RT-PCR." (PMID 25286393, 2014). "The protein expression levels of GOLPH3, p-AKT, p-mTOR, p-p70S6 and p-4E-BP1 in gastric cancer tissues were also significantly higher than in carcinoma-adjacent and paired normal tissues." (PMID 25286393, 2014). "Compared with carcinoma-adjacent and paired normal tissues, the mRNA expression levels of GOLPH3, AKT, mTOR, p70S6 and 4EBP1 in gastric cancer tissues were significantly higher." (PMID 25286393, 2014). "Gastric cancer involves numerous Golgi proteins such as GM130 (GOLGA2), GOLPH3, golgin-160 (GOLGA4), golgin-97 (GOLGA1) and golgin-84 (GOLGA7) that all play unique roles in cell processes including protein glycosylation, vesicle trafficking and Golgi structure maintenance." (PMID 37508488, 2023). "First, GOLPH3 expression levels were evaluated between gastric cancer tissues and adjacent noncancerous ones using immunohistochemical staining and quantitative analysis." (PMID 37508488, 2023). "Through this technique, it was observed that GOLPH3 expression was significantly higher in cancerous than noncancerous tissues—suggesting its possible connection to the progression of gastric cancer." (PMID 37508488, 2023). "Immunohistochemical analysis was used to evaluate the correlations between GOLPH3, phosphorylated mTOR (p-mTOR), phosphorylated Akt (p-Akt), phosphorylated p70S6 (p-p70S6), phosphorylated 4E-BP1 (p-4E-BP1) and the clinicopathological features of gastric cancer." (PMID 25286393, 2014). "In addition, GOLPH3 may primarily activate the Akt/mTOR signaling pathway via the activated mTORC1 complex rather than the mTORC2 complex, resulting in p70S6 and 4E-BP1 phosphorylation, thereby affecting gastric cancer." (PMID 25286393, 2014).
glioblastoma (11 papers, 2014 to 2025). The most malignant astrocytic tumor (WHO grade IV). "To study the involvement of GOLPH3 in the metabolism of glycolipids, we took advantage of the T98G cell line, a broadly used model of glioblastoma multiforme." (PMID 36142273, 2022). "The angiopep-2 was the peptide chosen for active targeting the GOLPH3-siRNA-liposomes to glioblastoma cells because of its specific binding to LRP-1 receptors expressed in the blood–brain barrier and tumor cells." (PMID 35456655, 2022). "Increasing evidence shows that GOLPH3 is overexpressed in different types of human tumors, including glioblastoma multiforme (GBM)." (PMID 33238647, 2020). "Increased levels of EGFR expression are frequently involved in deregulated cell proliferation in different types of tumors, including glioblastoma, therefore we evaluated the levels of this protein by immunoblot analysis upon GOLPH3 knockdown." (PMID 33238647, 2020). "In the present work, we report a distinct mechanism by which the overexpression of the oncoprotein GOLPH3 regulates EGFR in T98G cells of glioblastoma multiforme." (PMID 33238647, 2020). "In the present report, we show the case of the outcome on cell motility resulted from knocking down the overexpression of GOLPH3 in the human glioblastoma multiforme cell line T98G." (PMID 30779783, 2019). "It is not surprising then that regulation of cell migration is among the features attributed to the oncogenic capacity of GOLPH3 in different types of tumors, including glioblastoma." (PMID 30779783, 2019). "Large studies have found that GOLPH3 overexpression occurs in several human cancers, including epithelial ovarian carcinoma, renal cell carcinoma, glioblastoma multiforme, esophageal squamous cell carcinoma, and oral tongue cancer." (PMID 25286393, 2014). "GOLPH3 was also expressed in T98G glioblastoma multiforme cells and regulated EGFR trafficking." (PMID 40293576, 2025). "Furthermore, after GOLPH3 knock down in glioblastoma cell line, they observed that these cells expressed higher E-cadherin and lower MMP2." (PMID 38372877, 2024). "In another study, angiopep-2-decorated cationic lipid-poly (lactic-co-glycolic acid) (PLGA) NPs were designed for the dual delivery of gefitinib (an EGFR tyrosine kinase inhibitor) and golgi phosphoprotein 3 (GOLPH3) siRNAs that would act as an effective combinatorial for anti-glioblastoma therapy." (PMID 36358663, 2022). "However, although T98G cells have been broadly used as a model of glioblastoma multiforme, and that they seem to have acquired a unique transformation mechanism, it is unknown whether GOLPH3 plays a role in the tumorigenic features of these cells." (PMID 30779783, 2019). "Several papers provided evidence that GOLPH3 promotes cell proliferation and tumorigenicity of MDA-MB231 and MCF-7 breast cell lines and U251 and U87 glioblastoma cell lines." (PMID 32023813, 2020). "Golgi phosphoprotein 3 (GOLPH3), a peripheral membrane protein mostly localized at the trans-Golgi network, is overexpressed in several tumor types including glioblastoma multiforme (GBM), the most lethal primary brain tumor." (PMID 33238647, 2020). "Microtubule-associated protein 1 light chain 3 (LC3-II) levels were decreased in GOLPH3 knockdown U251 glioblastoma cells treated with or without rapamycin (an autophagy inducer)." (PMID 40293576, 2025).
lung carcinoma (11 papers, 2012 to 2025). "The expression of Golgi phosphoprotein 3(GOLPH3) was found to be correlated with copy number of 5p13 in human lung cancer, and gain or loss of function studies have proved that GOLPH3 was a genuine oncogene possessing strong transforming activity, which was induced in cancers with 5p amplification." (PMID 31921678, 2019). "The 5p13 amplification was shown to correlate with the expression of two genes in human lung cancer specimens (namely, GOLPH3 and SUB1)." (PMID 40136688, 2025). "Six studies 16, 25-29 provided GOLPH3 expression data in 711 lung cancer tissue samples and 461 adjacent normal lung tissue samples." (PMID 31737112, 2019). "Eight studies investigated the relationship between GOLPH3 expression and histologic type of lung cancer 11, 16, 24-29." (PMID 31737112, 2019). "During the initial search of the medical literature related to GOLPH3 and lung cancer, we identified 291 studies." (PMID 31737112, 2019). "The GOLPH3 gene is located on the human chromosome 5p13 and is frequently amplified in several solid tumor types, such as cancer of the lung, ovary, breast, prostate, and skin (melanoma)." (PMID 23056210, 2012). "Together with our recent identification of GOLPH3 as a radiosensitization target in lung cancer, the inhibition of GOLPH3 in radiotherapy appears to kill these “two birds” with one stone, so targeting GOLPH3 may be a promising strategy to achieve therapeutic benefit in radiotherapy." (PMID 36358544, 2022).
melanoma (10 papers, 2012 to 2022). A malignant, usually aggressive tumor composed of atypical, neoplastic melanocytes. "We revealed that enhanced GOLPH2 and GOLPH3 immunoreactivity in melanoma cells is associated with shorter cancer-specific overall survival (CSOS) and disease-free survival (DFS) in the whole group of patients." (PMID 27706081, 2016). "Interestingly, Golgi phosphoprotein 3 (GOLPH3), a Golgi-localizing protein, is encoded by 5p13, a region that is focally amplified in melanoma." (PMID 27896217, 2016). "High levels of both proteins in melanoma cells were associated with features of aggressive disease, i.e., greater thickness, ulceration, visible mitotic figures, weak lymphocytic infiltrate (relation with GOLPH3), lymphangioinvasion, nodal metastases and recurrence." (PMID 27706081, 2016). "GOLPH3 is important in endosomal-trans golgi signaling and has been shown to enhance endocytosis in melanoma cells via interaction with VPS35." (PMID 27896217, 2016). "The goal of our study was to examine the relationship of GOLPH2 and GOLPH3 expression levels in different compartments of primary melanoma tissue samples with other histopathological and clinicopathological parameters, especially with patient survival." (PMID 27706081, 2016). "Our results suggest that expression of GOLPH2 and GOLPH3 in TAMs is also clinically relevant for patients with melanoma." (PMID 27706081, 2016). "Using immunohistochemical stainings, we analyzed GOLPH2 and GOLPH3 expression in cancer cells, TAMs and CAFs in 100 primary melanoma tissue samples." (PMID 27706081, 2016). "Our results suggest that GOLPH2 and GOLPH3 play a role in melanoma progression and are potential targets for molecular-based therapies." (PMID 27706081, 2016). "Elevated level of GOLPH3 expression in melanoma cells was detected in 51% of cases (51/100), whereas low/absent expression in 49% of cases (49/100)." (PMID 27706081, 2016). "To conclude, consistent with findings in other cancer settings, our results suggest a role for GOLPH2 and GOLPH3 in melanoma pathogenesis, but functional studies are needed to evaluate the mechanisms involved." (PMID 27706081, 2016). "Human melanoma cells overexpressing GOLPH3 develop tumors faster than control cells when transplanted into immunodeficient animals." (PMID 25691054, 2015). "It has also been reported that high levels of GOLPH3 protein enhance the frequency of cell death in rapamycin-treated melanoma cells, suggesting that GOLPH3 expression can be used to predict rapamycin sensitivity in tumor therapy." (PMID 25691054, 2015). "Overexpression of GOLPH3 was shown to promote cell growth and proliferation in 1205 LU melanoma cells in vitro, and enhance tumor growth in xenotransplanted human melanoma and NSCLC cell lines in vivo." (PMID 25104140, 2014). "Amplification of GOLPH3 at 5p13 has been reported in diverse solid tumors, including lung, ovarian, breast, prostate, melanoma and pancreatic cancer." (PMID 25104140, 2014). "Hence, increased GOLPH3 expression, as observed in various cancers, including melanoma and NSCLC, enhances anterograde trafficking from the Golgi and leads to increased exocytosis of pro-metastatic factors, such as cytokines, growth factors, and Wnt molecules." (PMID 35563790, 2022). "We performed immunohistochemical analysis for GOLPH2 and GOLPH3 in 20 normal skin, 30 benign nevi and 100 primary melanoma tissue samples and evaluated their expression in three compartments: cancer cells, tumor-associated macrophages (TAMs) and cancer-associated fibroblasts (CAFs)." (PMID 27706081, 2016). "GOLPH2 and GOLPH3 are Golgi-related proteins associated with aggressiveness and progression of a number of cancers, but their prognostic significance in melanoma has not been investigated." (PMID 27706081, 2016).
melanoma (continued). "Stimulation of their metabolism and otherwise quiescent pathway (a manifestation of which would be upregulated GOLPH3) might be an attempt to restrict the expansion of melanoma by increase of ECM production." (PMID 27706081, 2016). "This is the first immunohistochemical analysis of GOLPH2 and 3 expression in a clinical melanoma cohort, and the first one addressing the significance of GOLPH2 and GOLPH3 expression in the stromal components." (PMID 27706081, 2016). "The expression of analyzed proteins in evaluated compartments was divided into two levels based on IRS score for melanoma cells (low: <6 vs. high: ≥6), the number of GOLPH2- and GOLPH3-positive macrophages (<20 vs. ≥20) and the number of GOLPH3-positive fibroblasts (<10 vs. ≥10)." (PMID 27706081, 2016). "In our experiment, GOLPH3-expressing fibroblasts were more frequent in thinner, non-ulcerated melanomas, with low mitotic rate and without lymphangioinvasion." (PMID 27706081, 2016). "Increased GOLPH3-positive fibroblasts were observed in thinner, non-ulcerated melanomas, with low mitotic rate and without lymphangioinvasion." (PMID 27706081, 2016). "Similarly, GOLPH3-expressing CAFs were more frequent in thin melanomas with low mitotic rate, without ulceration and lymphangioinvasion." (PMID 27706081, 2016).
ovarian carcinoma (10 papers, 2017 to 2024). A malignant neoplasm originating from the surface ovarian epithelium. "In ovarian cancer tissues and cell lines, GOLPH3 (high phosphoprotein 3) is a gene that encodes an oncoprotein, and Snail1 and other EMT transcription factors have been shown to regulate its expression by activating the Wnt/β-catenin signaling pathway." (PMID 35814427, 2022). "SNAIL and other EMT transcription factors (EMT-TFs) have been shown to activate expression of the GOLPH3 (Golgi phosphoprotein 3) gene, encoding for an oncoprotein frequently upregulated in ovarian cancer tissues and cell lines, through Wnt/β-catenin signaling activation." (PMID 31614568, 2019). "It has been suggested that the serum GOLPH3 concentration can be considered an index for the diagnosis of ovarian cancer and evaluation of surgical effects." (PMID 33680216, 2021). "Clearly, GOLPH3 expression was higher in epithelial ovarian cancer than in the borderline tumors and benign cystadenomas (P < 0.05)." (PMID 28332316, 2017). "As our data shows, GOLPH3 was upregulated in two of five ovarian cancer cell lines (SKOV3 and HEY) at both the mRNA and protein level compared with the normal immortalized cell line, Moody (P < 0.05)." (PMID 28332316, 2017). "There were 2 (13.33%) of the 15 cases of benign tumors, 3 (60%) of the five cases of borderline tumors, and 45 (84.91%) of the 53 cases of epithelial ovarian cancer that showed high expression of GOLPH3 protein." (PMID 28332316, 2017). "There were 2 of 6 cases of benign tumors, all 2 borderline tumors, and 13 of 15 cases of epithelial ovarian cancer that showed high expression of EDD protein (P < 0.05), while 1 of 2 borderline tumors and 11 of 15 cases of epithelial ovarian cancer showed high GOLPH3 expression (P < 0.01)." (PMID 28332316, 2017). "miR-509-3p directly targets XIAP to inhibit proliferation, and targets XIAP, Golgi phosphoprotein-3 (GOLPH3), and Wnt ligand secretion mediator (WLS) to regulate platinum sensitivity in chemoresistant ovarian cancer cells." (PMID 37386587, 2023).
esophageal squamous cell carcinoma (8 papers, 2012 to 2025). Esophageal squamous cell carcinoma (ESCC) is a type of esophageal carcinoma (EC) that can affect any part of the esophagus, but is usually located in the upper or middle third. "miR-126 can directly target the GOLPH3 to repress the proliferation in esophageal squamous cell carcinoma." (PMID 29534690, 2018). "The aim of this study was to examine GOLPH3 expression in patients with esophageal squamous cell cancer (ESCC) and explore its clinical significance." (PMID 23056210, 2012). "Previous study showed that miR-126, a tumor suppressor, promotes apoptosis or induced proliferation repression in many kinds of caners and also was reported to target GOLPH3 to suppress proliferation, migration and invasion in esophageal squamous cell carcinoma." (PMID 29534690, 2018).
non-small cell lung carcinoma (7 papers, 2016 to 2025). A group of at least three distinct histological types of lung cancer, including non-small cell squamous cell carcinoma, adenocarcinoma, and large cell carcinoma. "Recent studies indicated that GOLPH3 was highly expressed in malignant tumors, including colorectal, breast, renal, pancreatic, and non-small cell lung cancers, and closely associated with clinical staging and poor prognosis of the tumor." (PMID 27634904, 2016). "The oncogenic effect of GOLPH3 and its impact on the course of the disease have been demonstrated in studies on melanoma, colon adenocarcinoma, glioblastoma, and non-small-cell lung cancer." (PMID 37790749, 2023). "Finally, the levels of LCS protein and GOLPH3 proteins were significantly correlated in non-small-cell lung cancer samples from human patients." (PMID 40136688, 2025). "Importantly, in non-small-cell lung cancer specimens, the 5p13 amplification correlated with an increased mTOR expression and phosphorylation of the TOR substrate p70 S6 kinase, supporting the hypothesis that GOLPH3 might control mTOR activity in mammalian cells." (PMID 40136688, 2025).